SIGLEC9 (sialic acid binding Ig like lectin 9)
Diseases named in the same sentence as SIGLEC9 in open-access papers (continued):
Sharing a sentence is not in itself a finding about the gene and the disease.
cervical cancer (2 papers, 2024 to 2025). A primary or metastatic malignant neoplasm involving the cervix. "•SIGLEC9 is highly expressed in cervical cancer and linked to poor prognosis." (PMID 41418390, 2025). "Finally, flow cytometry confirmed that SIGLEC9+ TAMs were more abundant in cervical cancer tissue compared to normal cervical tissue, and high infiltration of SIGLEC9+ TAMs was associated with a poor prognosis in cervical cancer." (PMID 41418390, 2025). "Therefore, this study aims to clarify the expression and prognostic significance of SIGLEC9 in cervical cancer, while also exploring its correlation with Tumor-Associated Macrophages (TAMs) and T-cells in the tumor microenvironment." (PMID 41418390, 2025). "This study found that SIGLEC9 is highly expressed in cervical cancer and that its elevated expression is positively correlated with poor prognosis." (PMID 41418390, 2025). "The authors’ own database also demonstrated a correlation between high SIGLEC9 expression and advanced tumor stage in cervical cancer patients." (PMID 41418390, 2025). "To summarize, a high presence of SIGLEC9+ TAMs was correlated with poorer survival outcomes in cervical cancer." (PMID 41418390, 2025). "The study indicates that MUC1, secreted by cervical cancer cells, interacts with SIGLEC9 on macrophages and T-cells, promoting TAMs differentiation and inhibiting T-cell function, ultimately contributing to immune evasion in cervical cancer." (PMID 41418390, 2025). "This study investigates the role of Sialic acid-binding Immunoglobulin-Like Lectin-9 (SIGLEC9), a novel immune checkpoint, in Cervical Cancer (CC) and its interaction with immune cells in the tumor microenvironment." (PMID 41418390, 2025). "Overall, SIGLEC9 is highly expressed in cervical cancer and strongly correlates with FIGO staging and poor survival outcomes." (PMID 41418390, 2025). "In order to further verify the expression level of SIGLEC9 in cervical cancer, IHC and Western blotting were conducted to compare SIGLEC9 expression differences between cancer tissues and normal tissues." (PMID 41418390, 2025). "Consistent with previous studies, which have demonstrated that combined treatment with anti-SIGLEC9 and anti-PD-1/PD-L1 enhances anti-tumor efficacy, these findings further support the potential role of SIGLEC9 in immune-based therapies for cervical cancer." (PMID 41418390, 2025). "SIGLEC9 plays a crucial role in the progression and prognosis of cervical cancer through its interaction with TAMs and T-cells." (PMID 41418390, 2025). "•SIGLEC9+ TAMs and T-cells are highly enriched in the cervical cancer microenvironment." (PMID 41418390, 2025). "Based on these results, the authors hypothesize that targeting both SIGLEC9 and PD-1 in PD-1-resistant cervical cancer patients could improve the immune response and potentially prolong survival." (PMID 41418390, 2025). "In line with previous studies, these findings suggest that SIGLEC9+ T-cells could serve as a promising biomarker for the diagnosis of cervical cancer." (PMID 41418390, 2025). "Therefore, the authors confirmed the high infiltration of SIGLEC9+ T-cells in cervical cancer tissues through dual IF and FCM." (PMID 41418390, 2025). "Additionally, the study revealed that SIGLEC9 is predominantly expressed on macrophages and T-cells, with high levels of SIGLEC9+ TAMs and SIGLEC9+ T-cells observed in cervical cancer tissues." (PMID 41418390, 2025). "Consequently, these findings collectively suggest that SIGLEC9 is overexpressed in cervical cancer tissues." (PMID 41418390, 2025). "Additionally, Gene Set Enrichment Analysis (GSEA) was utilized to explore the biological functions of SIGLEC9 in cervical cancer." (PMID 41418390, 2025). "•High SIGLEC9+ TAM expression correlates with poor prognosis in cervical cancer." (PMID 41418390, 2025).
cervical cancer (continued). "Furthermore, protein levels of SIGLEC9 were investigated in cervical cancer patients and normal tissues from myoma of uterus patients who screened negative for cervical cancer and underwent total hysterectomy at the First Affiliated Hospital of Xinjiang Medical University." (PMID 41418390, 2025). "Furthermore, the research suggests that SIGLEC9+ TAMs may serve as a potential prognostic biomarker for cervical cancer." (PMID 41418390, 2025). "Therefore, the role of the MUC1/SIGLEC9 axis in cervical cancer deserves to be investigated." (PMID 41418390, 2025). "In addition, the authors collected single-cell suspension from cervical cancer tissues and normal controls, and detected the proportion of SIGLEC9+ CD4+T-cells, SIGLEC9+ CD8+T-cells and SIGLEC9+ M1 macrophages and SIGLEC9+ TAMs by flow cytometry." (PMID 41418390, 2025). "Moreover, SIGLEC9 is expressed on TAMs and T-cells, where it interacts with MUC1 secreted by cervical cancer cells, facilitating immune evasion." (PMID 41418390, 2025). "Although the functions of SIGLEC9 have been explored in certain types of cancer, there is currently no research on its impact on tumor immunity in cervical cancer." (PMID 41418390, 2025).
glioblastoma (2 papers, 2022 to 2023). The most malignant astrocytic tumor (WHO grade IV). "Siglec‐9 acts as an immune‐checkpoint molecule on macrophages in glioblastoma, restricting T cell priming and immunotherapy responses in glioblastoma patients." (PMID 37904707, 2023). "Although the functions of SIGLEC9 were explored in some types of cancer, the diagnosis value and underlying mechanism of SIGLEC9 in glioblastoma multiforme (GBM) have not been investigated." (PMID 35756603, 2022).
non-small cell lung carcinoma (2 papers, 2022 to 2023). A group of at least three distinct histological types of lung cancer, including non-small cell squamous cell carcinoma, adenocarcinoma, and large cell carcinoma. "A high SIGLEC9 expression in T cells is correlated with a decreased survival prognosis of non-small cell lung cancer patients." (PMID 35756603, 2022).
Sepsis (2 papers, 2022). Sepsis is defined as life-threatening organ dysfunction caused by a dysregulated host response to infection. "Afterwards, a sepsis/se-ARDS risk nomogram model that involves SIGLEC9, TSPO, CKS1B, and PTTG3P as the independent predictors was constructed." (PMID 35844622, 2022). "Moreover, the levels of immune cell infiltration in the progress of sepsis/se-ARDS promoted their further correlation analysis based on SIGLEC9, TSPO, CKS1B, and PTTG3P, the diagnostic biomarkers identified in the study." (PMID 35844622, 2022). "Further correlation analysis based on SIGLEC9, TSPO, CKS1B, and PTTG3P was carried out to identify the potential interactions and effects of these diagnostic biomarkers during sepsis/se-ARDS development." (PMID 35844622, 2022). "In summary, the present study identified SIGLEC9, TSPO, CKS1B, and PTTG3P as the genetic biomarkers and established a four-gene-based model for the effective diagnosis and risk prediction of sepsis/se-ARDS based on gene co-expression network." (PMID 35844622, 2022). "The expressions of four genes were remarkably related to each other, and it is apparent that the highly positive correlations between SIGLEC9 and TSPO and between CKS1B and PTTG3P were spectacularly remarkable at all the stages of sepsis/se-ARDS progression." (PMID 35844622, 2022). "During the development of sepsis/se-ARDS, the expressions of the identified biomarkers including SIGLEC9, TSPO, CKS1B and PTTG3P were all regulated remarkably and generally exhibited notable correlations with the stages of sepsis/se-ARDS." (PMID 35844622, 2022). "Both SIGLEC9 and TSPO were significantly upregulated on sepsis day 0 and then descended a bit more on sepsis day 7 (***P<0.001) during sepsis development, while both CKS1B and PTTG3P appeared to be steadily upregulated on sepsis day 0 and day 7 (*P<0.05)." (PMID 35844622, 2022). "SIGLEC9, TSPO, CKS1B, and PTTG3P all exhibited remarkable changes of upregulations in the sepsis group compared with control group in both datasets with P<0.05 (except for CKS1B in GSE28750), which proved the great diagnostic and predictive performance of these four biomarkers." (PMID 35844622, 2022). "Besides, SIGLEC9, TSPO, CKS1B and PTTG3P were considerably correlated with the infiltration of various immune cells including neutrophils and monocytes during sepsis/se-ARDS." (PMID 35844622, 2022).
bladder cancer (1 paper, 2023). "We treated the bladder cancer cell line T24 with sialidase, which could cut α-2, 3 or 2, 6-linked sialic acid from glycan and compared the amount of binding Siglec9-Fc on the cell surface using flow cytometry analysis." (PMID 37106774, 2023). "We compared glycosylation, sialic acid binding activity and dimerization of the Siglec9-Fc, and further detected ligands distribution on cancer cell lines of different tissue origin and bladder cancer tissue using produced protein." (PMID 37106774, 2023). "Considering all of these inquiries and our experiment results, further experimental validation is urgently needed to carefully uncover the interactions between Siglec9 and these identified proteins and figure out their biological consequences in the bladder cancer microenvironment." (PMID 37106774, 2023). "The confocal imaging results showed that the Siglec9-Fc signal mainly presented on the cell membrane (shown in red) and the binding signal almost disappeared after sialidase treatment in both T24 cells and bladder cancer tissue." (PMID 37106774, 2023).
esophageal squamous cell carcinoma (1 paper, 2023). Esophageal squamous cell carcinoma (ESCC) is a type of esophageal carcinoma (EC) that can affect any part of the esophagus, but is usually located in the upper or middle third. "This work studies the functions of sialic acid binding Ig like lectin 9 (SIGLEC9) and its related molecules in radioresistance and immunosuppression in esophageal squamous cell carcinoma (ESCC)." (PMID 36688997, 2023).
hepatocellular carcinoma (1 paper, 2024). A malignant tumor that arises from hepatocytes. "In skin cutaneous melanoma (SKCM), high SIGLEC9 expression correlated significantly with longer OS, progression-free interval, and disease-specific survival, while in hepatocellular carcinoma (HCC), SIGLEC9 overexpression on NK cells correlated with a worse prognosis." (PMID 39727942, 2024).
intestinal inflammation (1 paper, 2024). "Soluble SIGLEC9 was also studied as a potential therapeutic strategy in intestinal inflammation." (PMID 39727942, 2024).
metastatic tumors (1 paper, 2023). "In 38 primary tumors, the expression of SIGLEC9 in metastatic tumors decreased significantly." (PMID 37207210, 2023).
neuroblastoma (1 paper, 2021). Neuroblastoma (NB) is the most common solid, extracranial childhood tumor. "This analysis revealed that 1.918 of the 18.469 differentially expressed neuroblastoma transcripts were neutrophil-related, which included highly specific neutrophil markers such as FCGR3B, FPR1, S100A8/9, and SIGLEC9, among others." (PMID 34503071, 2021).
pancreatic ductal adenocarcinoma (1 paper, 2024). An infiltrating adenocarcinoma that arises from the epithelial cells of the pancreas. "Sialic acid expression was increased in pancreatic ductal adenocarcinoma (PDAC) as well, and α2,3 sialic acids are likely the main targets for SIGLEC9 in PDAC." (PMID 39727942, 2024).
prostate tumours (1 paper, 2024). "Transcriptomic analysis of PC patients using camcAPP58 revealed that mRNA levels of both SIGLEC7 and SIGLEC9 are significantly elevated in Gleason grade 9 (4+5) prostate tumours when compared with lower grade tumours." (PMID 38448753, 2024).
viral infections (1 paper, 2020). "In this review, we aim to discuss the similarities and differences between Siglec7 and Siglec9 and analyze their functions in virus infection and tumour progression in order to develop better anti-viral and anti-tumor immunotherapy in the future." (PMID 32322597, 2020). "Here, we aim to discuss the functions of Siglec7 and Siglec9 in virus infection and tumour progression." (PMID 32322597, 2020). "Whereas the most prominent Siglecs of immune regulation on NK cells are Siglec7 and Siglec9, this review will focus on the current research progress on the similarities and differences between Siglec7 and Siglec9 and their functions in tumour and virus infection progression." (PMID 32322597, 2020). "Although there are abundant evidences that show Siglec7 and Siglec9 expressed on NK cells are related to the HIV, HBV, and HCV infection, the exact mechanism of Siglec7 and Siglec9 involve in these viral infections requires further investigation." (PMID 32322597, 2020).
tumor (27 papers, 2020 to 2025). "Antibodies against SIGLEC-7 and SIGLEC-9 can suppress the conversion of macrophages into tumor-associated macrophages and reprogram the immunosuppressive tumor microenvironment, enhancing anti-cancer immunity." (PMID 39349440, 2024). "The single-cell analysis showed that SIGLEC9 was mainly expressed on tumor-associated macrophages (TAMs)." (PMID 36688997, 2023). "Infiltration of SIGLEC9-expressing immune cells has been associated with immunosuppression and tumor development." (PMID 36688997, 2023). "MUC1 had been found to engage with Siglec‐9, induced tumor‐associated macrophage‐like phenotype, and increased PD‐L1 expression in the tumor microenvironment." (PMID 34327857, 2021). "In the context of the associations with IL-4, IL-9, and TNF-α, high SIGLEC9 expression may have a suppressive effect on the immune system, helping the tumor evade elimination by immune cells." (PMID 39727942, 2024). "However, some researchers also showed that LGALS3BP acted as a tumor-associated immunomodulatory ligand for Siglec9." (PMID 37106774, 2023). "Moreover, SIGLEC9 is overexpressed on tumor-associated T cells and shifts macrophages toward tumor-promoting behaviors, suggesting that targeting SIGLEC9-related pathways might improve the antitumor response." (PMID 33796453, 2021). "Tumor-derived sialic acids dictate monocyte to macrophage differentiation via signaling through SIGLEC9, and provide new potential targets for cancer immunotherapy in PDAC." (PMID 41418390, 2025). "Nevertheless, further investigation into the endogenous DSG2 glycan profile in A375 cells is required to fully explore the glycan features contributing to DSG2 binding to Siglec‐9 in the tumor environment." (PMID 39813162, 2025). "While Siglecs are generally absent from human T cells, recent studies have indicated that Siglec‐9 expression can be induced in the tumor microenvironment, leading to the suppression of T cell activation upon interaction with sialylated glycans." (PMID 40071681, 2025). "The CD33-related Silane-Acid-Binding Immunoglobulin-like Lectin 9 (SIGLEC9) is of particular interest in tumor immunotherapy, which showed high affinity for α−2,3 and α−2,6 binding sialoglycans." (PMID 41418390, 2025). "Triggering of Siglec‐9 in human monocytes by tumor or stromal‐derived sialylated structures favors their differentiation toward TAMs that express CD163 and CD206." (PMID 40071681, 2025). "Subsequent analysis focused on macrophages in tumors, with the expression of SIGLEC9 in various cell subsets between tumor and normal tissues examined." (PMID 41418390, 2025). "This is partly accorded with the report that SIGLEC9 is mainly expressed on infiltrating immune cells during tumor progression." (PMID 36688997, 2023). "According to IHC results, SIGLEC9 expression was significantly increased in the tumor tissues or patients with radiotherapy (RT+) compared to those without (RT–)." (PMID 36688997, 2023). "Artificial inhibition of SIGLEC9 in TAMs suppressed the radioresistance and immunosuppressive tumor microenvironment (TME) in the co-cultured ESCC cells." (PMID 36688997, 2023). "In the results of our single-cell sequencing analysis, compared with normal samples, we found that SIGLEC9 expresses highly in three types of macrophages [macrophage (proliferating), macrophage, and microglia/microphage] in tumor samples." (PMID 35756603, 2022). "Then, we evaluated the expression correlation between SIGLEC9 and checkpoint members in tumor-induced immune response using Pearson correlation analysis with TCGA dataset." (PMID 35756603, 2022). "In TCGA database, SIGLEC9 expression was higher in tumor tissue than in adjacent normal tissue in LGG and GBM." (PMID 35756603, 2022). "Siglec7 and Siglec9 expressed on NK cells and their ligands play important roles in promoting the process of proliferation and migration of tumour cells." (PMID 32322597, 2020).